BRCA1 (BRCA1 DNA repair associated)
Diseases named in the same sentence as BRCA1 in open-access papers (continued):
Sharing a sentence is not in itself a finding about the gene and the disease.
breast cancer (continued). "It is also noteworthy that the low frequency of BARD1 PVs (less than 1%) in HBOC patients contrasts sharply with the much higher frequencies of BRCA1 and BRCA2 PVs, reinforcing the view of BARD1 as a gene conferring a moderate to low risk for breast cancer." (PMID 41301857, 2025). "In breast cancer, particularly TNBC, HRD predicts responsiveness to platinum agents and PARPi like talazoparib, especially in BRCA1/BRCA2-mutated cases." (PMID 40864792, 2025). "Pathogenic variants in BRCA1 and BRCA2 are associated with an increased risk of developing several types of cancer, including breast cancer." (PMID 40296163, 2025). "The OlympiA trial also demonstrated that adjuvant olaparib significantly improves invasive disease-free and overall survival in patients with germline BRCA1/2 mutations and high-risk HER2-negative early breast cancer." (PMID 40422528, 2025). "Key consensus points established specific age-based recontact practices for high penetrance CSGs, BRCA1, BRCA2 and PALB2, including recontact at 25 years to review breast cancer risk management and ovarian cancer risk management at gene-specific ages." (PMID 41159931, 2025). "BRRM’s large protective effect against breast cancer in BRCA1/2 carriers was confirmed, in contrast to that of RR-BSO." (PMID 40974500, 2025). "Among TNBC stage I-III (N = 321) and stage IV (N = 216) breast cancers, the most frequent alterations were mutations in PIK3CA (19.9% vs 21.3%), BRCA1/2 (11.5% vs 12.0%), ESR1 (0.31% vs 0%), PALB2 (0.9% vs 1.4%), and PD-L1 amplification (2.2% vs 4.6%)." (PMID 40421962, 2025). "To study functions of BRCA1 in breast cancer formation, we had previously generated mouse models carrying mammary-specific disruption of Brca1 using Cre-loxP system driven by Wap-Cre or MMTV-Cre." (PMID 41318657, 2025). "This important contribution notwithstanding, BRCA1/2’s definition as a ‘breast cancer gene’ has relegated it to be studied nearly exclusively in the context of cancer." (PMID 40276264, 2025). "The expression of BRCA1 in breast cancer cell lines, with the exception of MDA-MB-436 for which it was undetectable, was lower than that in HEK293." (PMID 40764992, 2025). "For patients with pathogenic variants of the genes BRCA1/BRCA2, the OlympiA trial achieved positive results in a high-risk population of hormone receptor-positive, HER2-negative breast cancers and variants of the genes BRCA1/BRCA2." (PMID 40002156, 2025). "This is compared with the guidance in place at the time of the meeting, which stipulated that individuals with a GPV in BRCA1/BRCA2/PALB2 were only eligible for breast cancer surveillance at age 25–30 years if they reached a 10-year risk of 8% or greater." (PMID 41159931, 2025). "The second predictive component, representing 6% of the total predictive variance, described a common trend of breast cancer cells unrelated to BRCA1 expression." (PMID 40863152, 2025). "HBOC due to PVs in BRCA1/2 genes accounted for 12% (60/491) of breast cancer and 17% (11/64) of ovarian cancer cases in our cohort, representing 61% (60/98) and 73% (11/15) of inherited cases, respectively." (PMID 40065011, 2025). "Other significant probability factors included breast cancer risk for BRCA1/2 carriers (p16), ovarian cancer risk for BRCA1/2 carriers (p15), uptake rate of RRM (p26), and uptake rate of both RRM and RRSO in BRCA1/2 carriers (p32)." (PMID 40567951, 2025). "HRD-positive luminal breast cancers with ATM or BRCA1/BRCA2 defects show tumor reduction with PARPi." (PMID 40864792, 2025). "Most PGVs seen in the present study were in BRCA1 (11.9% PGV prevalence, comprising 71% of all breast cancer susceptibility PGVs seen)." (PMID 39964682, 2025). "The aim of this study was to identify the characteristic transcriptomic pattern of monoallelic somatic BRCA1 inactivation and estimate its correlation with event-free breast cancer survival." (PMID 40870889, 2025).
breast cancer (continued). "We characterize alterations in PARP1, delineate effects on DNA damage ADPr signaling, and identify other changes in Olaparib-resistant BRCA1/2 mutant breast cancer cells." (PMID 40669753, 2025). "For example, miR-449a has been reported to target EME1 and downregulate BRCA2 and RAD51 in breast cancer, while miR-146 targets and/or downregulates FANCM and BRCA1 in cervical, gastric, and breast cancer cells." (PMID 41008855, 2025). "Its therapeutic relevance is compounded in breast cancer, particularly in BRCA1 or BRCA2 mutant cancers, where compromised homologous recombination repair (HRR) leaves a synthetic lethal dependency on PARP1-mediated repair." (PMID 41304924, 2025). "While most breast cancer cases are sporadic, about 5–10% are hereditary, often associated with pathogenic variants in the BRCA1 or BRCA2 (BRCA1/2 hereafter) genes." (PMID 40390061, 2025). "The 2024 American Society of Clinical Oncology (ASCO) guidelines recommend that BRCA1/2 testing be offered to every patient newly diagnosed with breast cancer under 65 years, and selected patients over 65 moving towards universal testing." (PMID 40390103, 2025). "A Chinese study from FUSCC revealed HER2 positivity in 7.3% of BRCA1 germline mutations and 8.7% of BRCA2 germline mutations in breast cancer." (PMID 39985003, 2025). "Some studies highlighted the superior performance of breast cancer-specific models in interpreting pathogenicity of variants in BRCA1, BRCA2, and other breast cancer-related genes." (PMID 41263939, 2025). "We focused on Polish founder mutations in BRCA1, BRCA2, PALB2, CHEK2, NBN and RECQL (18 alleles), which account for one-half of Polish breast cancer families." (PMID 40770660, 2025). "Another metabolomics study identified adenine (Ade), as well as other purine base derivatives in breast cancer cell lines and human plasma, as biomarkers of the BRCA1 genotype." (PMID 40863152, 2025). "In line with the observations by these authors, in breast cancer, we found that both BRCA1 and BRCA2 levels were significantly lower in TT compared with NAT, while in colorectal cancer only BRCA1 expression was significantly lower in TT." (PMID 41373491, 2025). "A 2023 study in the US reported that breast cancer patients carrying three genes, BRCA1, BRCA2, and ERCC2, were up to 56% more likely to be diagnosed with SPNs." (PMID 40391756, 2025). "Recently, the combination of DNA-binding ruthenium(II) polypyridyl complexes and olaparib showed synergy in triple-negative BRCA1-proficient breast cancer cells." (PMID 41155174, 2025). "The estimated prevalence of the BRCA1 and BRCA2 pathogenic variant carriers is up to 0.3% in the general population, 3% in women with breast cancer, 6% in women with early onset breast cancer, 10% in women with ovarian cancer, and 20% in high‐risk families." (PMID 39907309, 2025). "The combined results allowed us to highlight major traits of metabolism reprogramming induced by stable BRCA1 expression in breast cancer cells." (PMID 40863152, 2025). "MO compounds, including rutoside and vicenin-2, showed strong binding to BRCA-1 in breast cancer cell lines through molecular docking analysis." (PMID 40149610, 2025). "Inherited mutations in the tumor-suppressor genes like BRCA1 and BRCA2 confer a hereditary predisposition to breast cancer." (PMID 40904409, 2025). "Germline mutations in the BRCA1 and BRCA2 genes are well-established risk factors for distinct subtypes of breast cancer." (PMID 40867511, 2025). "Understanding the roles of lincRNAs in BRCA1-driven metastasis is critical to improving breast cancer therapies." (PMID 39997609, 2025). "The follow-up of patients with BRCA1 and BRCA2 mutations should be longer due to the risk of breast cancer." (PMID 40406472, 2025).
breast cancer (continued). "Only KTR14, KRT16, CXCL9, and CFD in BRCA1 Ovarian Cancer and TSPAN7 and CDKN2C in BRCA2 ovarian cancers were highly upregulated, and KANK4, MFGE8, LINC00346, and SA100A1 in BRCA1 mutated breast cancer, and MAGEA4 in BRCA2 breast cancers." (PMID 40647506, 2025). "Cancer risk-reducing surgeries were described for women with inherited breast cancer genes other than BRCA1/2." (PMID 40113717, 2025). "In earlier investigations, mutations in specific genes, notably BRCA1 and BRCA2, were identified as the primary instigators of breast cancer." (PMID 40809180, 2025). "A study from Saudi Arabia additionally highlighted significant germline mutations in the BRCA1 and BRCA2 genes in high-risk breast cancer patients, essential for understanding breast cancer susceptibility in Arab women." (PMID 41294844, 2025). "In this study, we showed that BRCA1 deficiency together with ERα signaling enhances SMYD3-SHCBP1 expression, which activates their downstream signaling, leading to the formation of mammary tumors in mice." (PMID 40157910, 2025). "First, using intact cell NMR metabolomics, we showed decreased cellular FA content in BRCA1-expressing breast cancer cells." (PMID 40863152, 2025). "Recruiting enough BRCA1 and BRCA2 mutation carriers for statistically significant findings is difficult, as they represent only a small subset of breast cancer patients." (PMID 40296163, 2025). "A case–control study included 1665 pairs of women with BRCA1 (n = 1243 pairs) and BRCA2 P/LP variants (n = 422 pairs) to assess the association between breastfeeding and breast cancer risk." (PMID 39858629, 2025). "Mutations in genes such as BRCA1, BRCA2, and PIK3CA interfere with DNA repair and trigger oncogenic signaling pathways in breast cancer." (PMID 40565055, 2025). "In breast cancer, BRCA1 has been reported as a target of UHRF1-mediated methylation, while in non-small-cell lung cancer, RASSF1, CYGB, and CDH13 have been identified as UHRF1-regulated methylation targets." (PMID 41373864, 2025). "BRCA gene mutations, particularly in BRCA1, are significantly enriched in patients with triple-negative breast cancer (TNBC) compared to other breast cancer subtypes." (PMID 41301002, 2025). "To unravel the extent of metabolic reprogramming of BRCA1-expressing breast cancer cells, we used several untargeted metabolomics platforms and transcriptional expression of metabolism-related genes." (PMID 40863152, 2025). "Recent data from the Hereditary Breast Cancer Clinical Study Group support a survival benefit of MRI in unaffected BRCA1/2 carriers partaking in MRI surveillance programs." (PMID 40275390, 2025). "Given the high proportion of BRCA1 and 2 mutation carriers in AYA breast cancers, second cancers are a relatively common event in these women reaching about 10% contralateral breast cancer cumulative incidence in 15 years." (PMID 40809018, 2025). "In summary, in the Colombian population, there is a great diversity of germline mutations in genes other than BRCA1 and BRCA2 that are associated with breast cancer." (PMID 40259910, 2025). "Altogether, these data provide a strong correlation between elevated levels of SMYD3 in PABC, BRCA1, and invasive lobular breast cancers, making it a very important therapeutic target to interrogate in breast cancer." (PMID 40157910, 2025). "To exclude the system interference in HP5008 cells, we conducted CRISPR-Cas9 knockouts of Rad51b, Ezh2, Suz12 and Aebp2 in Brca1-mutant 545 cells, which were isolated from a primary mammary tumor of a Brca1-MSK mouse." (PMID 41318657, 2025). "Previous studies in breast cancer cells have shown that PRMT5 activity supports DNA repair by promoting BRCA1 mRNA stability through m6A demethylation pathways." (PMID 40919714, 2025).
breast cancer (continued). "It is worth noting that, in current clinical practice, international guidelines recommend a rational use of NGS in advanced breast cancer, prioritizing targeted testing for known actionable mutations (e.g., PIK3CA, BRCA1/2, ESR1, etc.)." (PMID 41018107, 2025). "Olaparib, the first FDA-approved PARP inhibitor, has been approved as an adjuvant treatment option for HR+/HER2- ABC with germline BRCA1 or BRCA2 mutations or early-stage, high-risk breast cancer that has received neoadjuvant or adjuvant chemotherapy." (PMID 40134916, 2025). "Germline pathogenic and likely pathogenic variants in the BRCA1 and BRCA2 genes (BRCApv) account for 3–5% of breast cancer (BC) incidence and are linked to hereditary breast and ovarian cancer syndrome." (PMID 40408052, 2025). "Several preclinical studies have demonstrated that BRCA1/2-related breast cancer cell lines exhibit varying degrees of sensitivity to chemotherapeutic agents that induce DNA damage, such as poly (ADP-ribose) polymerase (PARP) inhibitors." (PMID 40427118, 2025). "Mutations in BRCA1 and BRCA2 genes, crucial for DNA repair, lead to breast cancer and genomic instability." (PMID 41333220, 2025). "Germline BRCA1/2 mutations are associated with higher pCR rates and improved DMFS in breast cancer patients treated with NCT." (PMID 40405286, 2025). "In population-based studies, BRCA1 and BRCA2 P/LP variants were associated with a significantly increased risk of breast cancer, with an odds ratio (OR) ranging from 7.62 to 10.57 and 5.23 to 5.85, respectively." (PMID 39858629, 2025). "Chemotherapy receipt varied significantly by pathogenic variant and age at diagnosis, with BRCA1 carriers, PALB2 carriers, and early-onset breast cancers diagnosed under 30 years of age receiving chemotherapy in greater than 80% of cases." (PMID 40275390, 2025). "BRCA1 and BRCA2 mutations, known risk factors for breast cancer globally, are also present among Arab women, though specific mutations and their frequencies can vary significantly." (PMID 41294844, 2025). "Chemotherapy was administered in 70.9% of index breast cancer cases diagnosed in BRCA1/2 and PALB2 carriers." (PMID 40275390, 2025). "It is established that mutations in the BRCA1 or BRCA2 gene underlie sensitivity to PARP inhibitors in cancer cells, most notably in breast cancer." (PMID 40025053, 2025). "Toxicities limit combination of PARP inhibitors (PARPi) and chemotherapy in patients with germline BRCA1 and BRCA2 pathogenic variant (gBRCAm) breast cancer." (PMID 40360463, 2025). "This procedure reduces the risk by up to 95% in women with germline mutations in the BRCA1 or BRCA2 genes and by up to 90% in women with a strong family history of breast cancer." (PMID 40243654, 2025). "In this study, we found that the enzymatic activity of PARP1 is dispensable for the survival of a BRCA1 mutant (BRCA1m) breast cancer model." (PMID 41459749, 2025). "This increases the cumulative chance of developing breast cancer by the age of 70 years from 40% to 87% for BRCA1 and from 27% to 84% for BRCA2 carriers." (PMID 41273720, 2025). "BRCA1 and BRCA2 (BRCA1/2) mutation screening is recommended for patients with advanced breast cancer or early breast cancer suspected to have hereditary origins based on family history or tumor characteristics." (PMID 40065879, 2025). "BRCA1 expression was shown to decrease glucose consumption and increase oxygen consumption of breast cancer cells, as well as increase mitochondrial respiration and ATP content of ovarian cancer cells." (PMID 40863152, 2025). "The breast cancer cell line MDA-MB-231 exhibited increased cell sensitivity to PARPi upon depletion of BRCA1 or Cezanne." (PMID 41359628, 2025).
breast cancer (continued). "Despite advancements in genetic testing and expanded eligibility criteria, underutilisation of germline testing for pathogenic variants in BRCA1 and BRCA2 (BRCA) remains evident among breast cancer (BC) patients." (PMID 39876688, 2025). "While BRCA1/2 mutations are the standard in clinical testing, other HRR pathway genes, such as PALB2 and RAD51C, have potential applications in determining breast cancer treatment." (PMID 38397152, 2024). "For BRCA1, relative to the before-1940 cohort, the breast cancer RRs (95% floating-CI27) were 2.5 (1.8–3.4), 2.9 (1.9–4.6) and 3.3 (1.9–5.7) for the three later birth cohorts, respectively (eTable 6)." (PMID 38333895, 2024). "Suppressing LYN kinase activity in BRCA1-defective cell lines as well as in in vitro cultures of Brca1-null mouse mammary tumours is deleterious to their growth." (PMID 38149669, 2024). "Among patients with BRCA1/2-mutant breast cancer, dramatic initial responses to PARPi drugs, such as olaparib and talazoparib, led to their FDA approval as monotherapy." (PMID 38956205, 2024). "A point mutation (E168Q) in the OLA1 gene is linked to apoptosis, preventing the formation of a complex with BRCA1 and BARD1, and is associated with poor outcomes in breast cancer." (PMID 38889130, 2024). "When we examined immunosuppressive lipid shedding by breast cancers, we found that treatment of breast cancer cell lines and Brca-1 mutant mice with Lipitor restored anti-tumor immune responses and decreased mammary hyperplasia in vivo." (PMID 39596374, 2024). "BC that is linked withgerminal mutations in BRCA1 has a triple negative phenotype(70–85 %), while ER-positive cases can be detected in carriersof mutations in the BRCA2, ATM, CHEK2 and PALB2 genes." (PMID 39027127, 2024). "Carriers of BRCA1 and BRCA2 mutations face a cumulative breast cancer risk of 72% and 69% respectively by the age of 80." (PMID 38167124, 2024). "More breast cancers were detected in BRCA1 carriers than in BRCA2 patients (1% RRM vs. 27% surveillance in BRCA1; 0% RRM vs. 19% surveillance in BRCA2)." (PMID 38248108, 2024). "Having a close blood relative with a history of breast cancer and the presence of inherited mutations in genes like the BReast CAncer genes 1 (BRCA1) and 2 (BRCA2) raises breast cancer risk in approximately 5%–10% of women." (PMID 38807767, 2024). "More than half of the respondents (55%) were aware that mutations in the BRCA1 or BRCA2 genes predispose women to cervical cancer and breast cancer." (PMID 39728052, 2024). "Overall survival and mortality among patients with germline BRCA1/2-mutated, HER2-negative advanced breast cancer." (PMID 38817906, 2024). "In hereditary BRCA1/2 PV breast cancers, the knockout of BRCA proteins results in impaired histone deacetylation." (PMID 39682099, 2024). "Germline mutations in BRCA1 are present in 11–20% of TNBC cases, and TNBC accounts for 70% of breast cancers in BRCA1 mutation carriers." (PMID 39409110, 2024). "In breast cancer cell lines with BRCA1 promoter methylation, low expression levels of BRCA1 mRNA and protein were observed, and these cell lines showed cisplatin sensitivity comparable to that of BRCA1 mutated cells." (PMID 38256203, 2024). "The overexpression of LSD-1 in breast cancer has been correlated with a downregulation of BRCA1, especially in aggressive cancers such as basal-like and TNBC." (PMID 39682099, 2024). "In this study, we conducted a CRISPR-dCas9 interference screen in a BRCA1/2-proficient breast cancer cell line to identify genes that modulate the cell response to the PARP inhibitor olaparib and identified IRF9 as a candidate." (PMID 39062738, 2024).